GPX4 (glutathione peroxidase 4)
Diseases named in the same sentence as GPX4 in open-access papers (continued):
Sharing a sentence is not in itself a finding about the gene and the disease.
colitis (continued). "Results showed that compared with sham group, pharmacological inhibition of GPX4 significantly reversed SYD-induced alleviation of colitis system and restoration of barrier dysfunction in colitis rats." (PMID 35974396, 2022). "In our study, colonic protein expression and mRNA level of GPX4 were all decreased after TNBS treatment, and SYD administration enhanced GPX4 expression in colitis rats." (PMID 35974396, 2022). "SYD alleviated chemically induced colitis by activation of GPX4, inhibition of ferroptosis in epithelial cells and further restoration of barrier function." (PMID 35974396, 2022). "Recent studies have shown that Shaoyao Decoction can reduce TNBS induced colitis by activating Gpx4, inhibiting ferroptosis of intestinal epithelial cells, and restoring barrier function." (PMID 36714107, 2022). "SYD alleviated chemically induced colitis by increasing GPX4 transcription and further inhibited ferroptosis in epithelial cells." (PMID 35974396, 2022). "Based on the findings of transcriptomics results, whether the therapeutic effect of XYP on colitis is also involved in the pathway of ferroptosis and oxidative stress, we examined the levels of Fe, GPX4, GSH, SOD and MDA." (PMID 41424783, 2025). "In general, the up-regulation of the Nrf2/Keap1 and GPx4 signalling pathways may be one of the pivotal mechanisms by which GSH-Se alleviates DSS-induced colitis." (PMID 40076493, 2025). "Similarly, DSS-induced colitis suppressed the expression of key ferroptosis-regulating proteins such as GPX4, SLC7A11, and SLC3A2, while elevating HO-1 levels as a compensatory response to oxidative stress." (PMID 39940407, 2025). "ACSL4 was downregulated and Gpx4 was upregulated by HT treatment in colitis." (PMID 39064786, 2024). "We also examined whether the colitis-protective mechanism of PD is mediated by ferroptosis through the Nrf2/Slc7a11/Gpx4 axis in vivo." (PMID 39877390, 2024). "Their findings demonstrated that Shaoyao Decoction could mitigate colitis by modulating the GPX4-regulated ferroptosis pathway within epithelial cells." (PMID 39036600, 2024). "Moreover, the supplementation of HT significantly downregulated the increased ACSL4 in DSS-induced colitis while it upregulated the decreased Gpx4 both in mRNA and protein expression, suggesting that HT suppressed ferroptosis in colitis in vivo." (PMID 39064786, 2024). "Animal studies have shown that mice lacking GPx4 are more susceptible to colitis compared to wild-type mice, highlighting the important role of GPx4 in protecting the intestine from LPO damage and maintaining intestinal homeostasis." (PMID 38965216, 2024). "However, our unbiased ubiquitination MS sequencing data and in vivo experiments support that SLC3A2/GPX4–mediated lipid peroxidation production signaling played a dominant role in controlling colitis and CAC." (PMID 39688910, 2024). "Induction of GPX4 can mitigate experimental colitis by suppression of ferroptosis." (PMID 37153794, 2023). "To confirm whether ferroptosis is involved in the enhanced susceptibility from early-life microbial dysbiosis to colitis, we then measured COX-2, GPX4 levels, and iron contents in the colonic tissues of AIMD mice." (PMID 37040489, 2023). "Besides, GPX4 expression is decreased in chemically induced colitis and inhibition of GPX4 aggravates the pathological process of IBD." (PMID 35974396, 2022). "All the five ingredients in SYD exerted significant anti-colitis effects and inhibition effects of ferroptosis in epithelial cells, indicating that the five ingredients act as the key therapeutic material basis of SYD-induced anti-colitis effects based on GPX4 agonistic activity." (PMID 35974396, 2022). "Moreover, we observed increased PTGS2 and decreased GPX4, which were generally used as biomarkers of ferroptosis, in the colonic IECs from experimental colitis mice, compared with the vehicle mice." (PMID 32015337, 2020).
colitis (continued). "Therefore, to further confirm this result in vivo, we regulated the level of HIF-1α while simultaneously administering the GPX4 inhibitor RSL3 to DSS-induced acute colitis mice to observe changes in the mice’s general condition, intestinal barrier function, and ferroptosis." (PMID 40691131, 2025). "Notably, this specific GPX4 deletion did not enhance susceptibility to dextran sodium sulfate (DSS)-induced colitis in mice with varied iron diets but showed vulnerability in mice with a vitamin E-deficient diet." (PMID 38260380, 2024). "Moreover, inducing selenoprotein expression, such as GPX4, with SeNPs in vivo can regulate intestinal microenvironment immunity and gut microbiota to attenuate radiation‐induced colitis by inhibiting oxidative stress and maintaining microenvironment immunity homeostasis." (PMID 39348242, 2024). "Besides, SYD also increased GPX4 mRNA level in colitis rats, indicating that SYD may increase GPX4 expression by modulating transcription of GPX4 gene." (PMID 35974396, 2022). "In conclusion, FXR is compromised in colitis, and restoring FXR has a protective effect on colitis by suppressing ferroptosis via direct transactivation of SLC7A11 and stabilizing GPX4." (PMID 40681992, 2025). "In a DSS‐induced colitis mouse model, the DSS group showed higher expression of ACSL4 and lower expression of GPX4 and FTH1 compared to the WT group." (PMID 41098076, 2025). "This study highlights that FXR exerts therapeutic effects against colitis by antagonizing ferroptosis via transactivation of SLC7A11 and increasing GPX4 stability." (PMID 40681992, 2025). "As an indispensable cofactor for the antiferroptotic role of GPX4, GSH was also improved by Fex in DSS-induced colitis." (PMID 40681992, 2025). "A consistent pattern was observed across both models: the protein level of GPX4, a master inhibitor of ferroptosis, was significantly restored in the SCD inhibitor-treated groups compared to the colitis control groups." (PMID 41515900, 2025). "Numerous studies have demonstrated that hallmark features of ferroptosis—including iron overload, inactivation of glutathione peroxidase 4 (GPX4), and oxidative stress—are prevalent in tissues from IBD patients as well as in experimental colitis models." (PMID 41312366, 2025). "Our findings indicated that GPX4 mediated ILC3s, particularly the NKp46+ILC3 subpopulation, specifically regulating colitis, accompanied by alterations in ferroptosis characteristics of ILC3s and their secretion capacity for IL-22 and IL-17A." (PMID 39300068, 2024). "Consistent with the results from in vitro experiments, we observed a reduction in the expression of Gpx4, while Acsl4 and Alox5 were upregulated in the DSS‐induced colitis model at the transcription level." (PMID 38340032, 2024). "An iron‐overloaded diet can result in iron‐overload‐induced colitis, with mechanisms involving the downregulation of the NRF2/GPX4 signaling pathway, leading to elevated MDA, ROS, and Fe2+ levels." (PMID 39568773, 2024). "Meanwhile, no apparent difference was observed in ferroptosis-related proteins between 2 groups of mice after DSS treatment, including ACSL4, GPX4, and FTH1, suggesting that ferroptosis contributed minimally to the aggravated colitis in Gab1IEC-KO mice." (PMID 36795486, 2023). "In DSS-induced colitis mouse model, HMGB1 upregulation accompanied by changes in TLR4, NF-κB, and GPX4 expression and ferroptosis-related genes upregulation, while inhibition of HMGB1 attenuated inflammation, restored barrier function, and reversed ferroptosis." (PMID 40689397, 2025). "In a DSS-induced colitis model, we observed that activation of the HMGB1/TLR4/NF-kB pathway resulted in decreased GPX4 expression, accompanied by increased mRNA levels of ferroptosis-related indicators (PTGS2, IREB2, CS, RPL8, and ATP5G3), which was further verified by cellular experiments." (PMID 40689397, 2025).
colitis (continued). "Interestingly, IHC staining results revealed that, except for TXNRD1, the expression levels of ACSL4 and LPCAT3 in colitis mice were higher than those in the normal control group, while SLC7A11 and GPX4 displayed the opposite consequence." (PMID 40691131, 2025). "In our present study, we observed that DSS-induced colitis was accompanied by enhanced colonic iron, malondialdehyde (MDA) levels, and COX-2 (cyclooxygenase-2) signals, and reduced GPX4 (glutathione peroxidase 4) levels in the colon tissues." (PMID 37040489, 2023). "Moreover, ERC-exos treatment further enhanced the levels of GSH and the expression of GPX4 but reduced the levels of iron, MDA, and expression of ACSL4 in the colon of colitis mice." (PMID 36045952, 2022). "Similar findings were obtained in vivo using DSS-induced colitis mice model, where treating these mice with exogenous furin relieved DSS-induced colitis, a mechanism involving the activation of Nrf2 and the upregulation of GPX4." (PMID 36552895, 2022). "In our GEO data analysis of UC patients, “Pyroptosis”, “Regulated necrosis”, and “Apoptosis” were positively correlated with UC patients, which supports our result showing increased expression of RIPK1 and RIPK3, but not ALOX12 and GPX4, in the acute colitis model." (PMID 38491049, 2024). "Consistent with the advanced results, GPX4 expression and GSH synthesis were increased in the ERC-exos-treated group, while iron, MDA, and the expression of ACSL4 were decreased in the DSS-induced group, which suggested that ERC-exos can downregulated ferroptosis in colitis." (PMID 36045952, 2022). "We also recognize a limitation that the mechanisms of NF-κB and STAT3 on regulating the SLC7A11/GSH/GPX4 antioxidant axis and XJS targeting FGL1 to inhibit colitis are not verified in vitro, which will be conducted in a future study." (PMID 37153794, 2023). "RSL3 is an inhibitor of GPx4, and studies have found that the PERK inhibitor GSK414 not only suppresses the expression of the ER stress signaling pathway eIF2α/ATF4/CHOP induced by RSL3 but also reduces cellular ferroptosis, improving experimental colitis in mice." (PMID 38965216, 2024).
colon cancer (42 papers, 2020 to 2025). "GPX4 is a protein associated with poor prognosis, potentially inhibiting ferroptosis in colon cancer cells through specific signaling pathways and interacting synergistically with HSPA5." (PMID 37842645, 2023). "GPX4 expression was found negatively associated with OS in cholangiocarcinoma, colon cancer, and LUSC patients." (PMID 36443446, 2022). "GPX4 and SELENOP polymorphisms also interact to affect colon cancer risk, providing additional support for an interaction between selenium status and GPX4 alleles." (PMID 32806741, 2020). "However, the rate of invasive colonic tumors in myeloid Gpx4-deficient AOM mice (∼10%) was about 10-fold lower than that in Apc/Dok3 mice (100%)." (PMID 36970719, 2022). "Consistent with the sequencing results, the results of immunohistochemistry also support that the expression level of GPX4 in colon cancer and liver cancer was significantly higher than that in the corresponding normal tissues." (PMID 41142608, 2025). "Mechanistically, the combination of LT and erastin downregulates the overexpression of GPX4 in colon cancer cells." (PMID 40552277, 2025). "E. coli targeted colon tumors, where Cu2O consumed endogenous H2S, and the generated Cu+ inactivated GPX4 and promoted the aggregation of DLAT." (PMID 40200790, 2025). "Collectively, these findings demonstrate that the MSL1-KCTD12 axis regulates SLC7A11 and GPX4, thereby modulating Erastin-induced ferroptosis in colon cancer cells." (PMID 40221412, 2025). "Thereby, MDM4 enhances the stability of GPX4 protein, inhibiting ferroptosis, increasing the resistance of colon cancer patients to chemotherapy, and promoting colon cancer progression." (PMID 39543140, 2024). "Surprisingly, in a genetic mouse model of colon tumors, the deletion of GPX4 specifically in colon epithelial cells increased tumor burden but decreased oxidized glutathione." (PMID 38260380, 2024). "In our study, MDM4 is found to upregulate the TRIM21 expression level to inhibit the ubiquitination of GPX4, and promotes colon cancer progression." (PMID 39543140, 2024). "In mice with a myeloid cell-specific deletion of glutathione peroxidase 4 (Gpx4), a crucial ROS scavenger, more invasive colon tumors developed after repeated injections of the carcinogenic agent azoxymethane." (PMID 38474175, 2024). "We also found the expression of GPX4 in colon cancer tissues was higher than that in normal tissues through public database analysis." (PMID 37658132, 2023). "Compared to normal tissues, we found that the expression of GPX4 was higher in colon cancer tissues." (PMID 37658132, 2023). "For instance, NGAL decreases intracellular iron levels and stimulates the expression of glutathione peroxidase 4 to prevent membrane lipid peroxidation in colon cancer cell lines." (PMID 37760777, 2023). "The present study showed HMGB1 expression were positively correlated with GPX4 and p-p65, these clinical findings suggest the therapeutic targets for colon cancer." (PMID 32514250, 2020). "Pull-down, CoIP and immunohistochemistry assays were performed to further investigate the molecular mechanisms of HMGB1 and GPX4 in colon cancer." (PMID 32514250, 2020). "In conclusion, our results provided the evidences showing that acetylated HMGB1 can interact with GPX4, leading to oxidative stress and inflammation via NF-kB in colon cancer cells." (PMID 32514250, 2020). "And then correlation analysis showed that HMGB1 was positively correlated with GPX4 and p-p65, providing the therapeutic target for colon cancer." (PMID 32514250, 2020).
colon cancer (continued). "Collectively, our findings first demonstrate that acetylated HMGB1 can interact with GPX4, leading to inflammation, and providing therapeutic strategies targeting HMGB1 and GPX4 for colon cancer." (PMID 32514250, 2020). "In this study, our immunoprecipitation results showed that HMGB1 can interact with GPX4 in both colon cancer cells, thus leading to ROS accumulation and inflammation stimulated by LPS, identifying the novel mechanism for colon cancer therapy." (PMID 32514250, 2020). "Subsequently, by utilizing 50 pairs of colon tumor tissues, we analyzed the expression and correlation about HMGB1, GPX4 and p-p65, and then evaluated their correlation in colon cancer." (PMID 32514250, 2020). "To investigate whether TAGP induces colon cancer cell death through ferroptosis, we examined the expression of GPX4, an essential regulator of ferroptosis, in SW480 and HCT116 cells using western blot analysis." (PMID 40730487, 2025). "Furthermore, we found that MSL1 downregulation, via modulation of KCTD12, suppresses the expression of key negative regulators of ferroptosis, SLC7A11 and GPX4, thereby promoting Erastin-induced ferroptosis in colon cancer cells." (PMID 40221412, 2025). "Additionally, we investigated the protein expression of PCBP1, PCBP2 and GPX4 in colon cancer patients via immunofluorescence staining." (PMID 40619432, 2025). "Additionally, luteolin and erastin effectively reduced colon cancer cell viability and growth, increasing ferroptosis and decreasing glutathione peroxidase 4 (GPX4) expression." (PMID 40916076, 2025). "In addition, GPX4 was expressed at higher levels in primary and metastatic colon cancer tissues than in healthy colon tissues." (PMID 40746894, 2025). "In order to explore whether the expressions of CST1 and GPX4 are also related in other tumor tissues, we selected colon cancer tissues and cells for experiments." (PMID 36369321, 2023). "They found that GPX4 was positively expressed in the colon tumour tissues." (PMID 37807410, 2023). "Therefore, inhibition of GPX4 to induce ferroptosis in cancer cells may be a therapeutic strategy for some tumor, just as RSL3 inhibition of GPX4 induces ferroptosis in colon cancer." (PMID 36387147, 2022). "Our data demonstrate that Tempol, when combined with the GPX4 inhibitor ML210, exerts selective and pathway-specific synergy in gastric and colon cancer cells." (PMID 41150804, 2025). "Utilizing Western blot analysis, we examined the expression levels of key ferroptosis-related proteins including GPX4, xCT, FPN1, and DMT1 in colon cancer cells following treatment with PMFs." (PMID 40290432, 2025). "Matrine shows antiproliferation and promotes the ferroptosis of colon cancer cells by upregulating the ferroptosis-inducing ATF4 gene and downregulating the ferroptosis-inhibiting genes (GPX4 and SLC7A11)." (PMID 38892270, 2024). "Mechanistically, gallic acid regulates the ferroptosis of colon cancer cells by upregulating the ferroptosis-inducing ATF4 gene and downregulating ferroptosis-inhibiting genes (GPX4 and SLC7A11)." (PMID 38892270, 2024). "Above results have proved the connection between HMGB1, GPX4 and p-p65 in SW480 and HCT116 cancer cells, we thereby explored the HMGB1, GPX4 and p-p65 correlation in colon cancer tissues." (PMID 32514250, 2020). "In addition, RSV can induce iron death in colon cancer cells by promoting lipid peroxidation and inhibiting the protein expression of SLC7A11 and GPX4." (PMID 40490812, 2025).
colon cancer (continued). "Moreover, curcumin down-regulates the protein expression of GPX4 and Solute carrier family 7 member 11 (SLC7A11) to induce ferroptosis in colon cancer (HCT-8) and follicular thyroid cancer (FTC-133 and FTC-238) cells." (PMID 40490812, 2025). "Analysis of the TCGA colon cancer database and subsequent immunohistochemical analysis on tissue microarrays confirmed higher GPX4 expression in colon cancer tissues compared to adjacent normal tissues." (PMID 39543140, 2024). "We performed WB detection of CST1 and GPX4 proteins in 5 matched colon cancer tissues and adjacent normal intestinal mucosal tissue samples." (PMID 36369321, 2023). "Treatment with doxorubicin significantly reduced the tumor mass composed of HCT116 (a human colon cancer cell line) cells with gpx4 knockdown compared to the control nude mice without gpx4 knockdown." (PMID 36675129, 2023). "From this point of view, GPx8 is even more important than GPx4, which is absent in the mucosa of almost 71% of cases of colon tumors." (PMID 35208621, 2022). "The high-mobility group box-1 (HMGB1) and glutathione peroxidase 4 (GPX4) are responsible for inflammation, but the relationship between HMGB1 and GPX4 remains unknown about inflammation in colon cancer." (PMID 32514250, 2020). "An inverse correlation between GPX4 expression and accumulation of 8-hydroxy-2′-deoxyguanosine, the end-product of oxidation, has been observed in diffuse large B-cell lymphoma (DLBCL), whereas GPX4 expression is upregulated, and oxidative stress is reduced in colon cancer." (PMID 37626774, 2023). "Proteomic data of 97 colon tumor tissues from TCGA-CPTAC dataset validated the negative correlation of PMP70 and GPX4 protein level (r = –0.3376, P = 0.0007)." (PMID 40229252, 2025).